LINC01101 (long independently transcribed non-coding RNA 1101)
Synonyms: FLJ14816
Gene: Long non-coding RNA gene on chromosome 2 (120,464,322 to 120,466,528, reverse strand). Ensembl gene ENSG00000280409.
Diseases named in the same sentence as LINC01101 in open-access papers:
LINC01101 is named in the same sentence as 3 diseases in open-access papers, as found by Europe PMC text mining. Sharing a sentence is not in itself a finding about the gene and the disease.
LINC01101 shares sentences with these, for which no sentence is quoted: asthma (1 paper); diabetes (1); nicotine addiction (1).